TRAF6 (TNF receptor associated factor 6)
Diseases named in the same sentence as TRAF6 in open-access papers (continued):
Sharing a sentence is not in itself a finding about the gene and the disease.
tumor (continued). "miR-146a has been identified as a tumor suppressor through down-regulation of the NFkB activators IRAK1 and TRAF6." (PMID 23554878, 2013). "Among the genes involved in the extrinsic route, TRAIL-R1 (DR4) and TRAIL-R2 (DR5) were expressed at the highest level in both low and high MKI tumours, followed by TRAF-1, TRAF-6, Fas and Fas-ligand." (PMID 16755292, 2006). "Our results demonstrate that, through its deubiquitinating activity, USP11 enhances the stability of EGFR and TRAF6, crucial mediators in these pathways, ultimately promoting CRC tumorigenesis, cell migration, proliferation, colony formation, and 3D tumor spheroid formation." (PMID 41419456, 2025). "TRAF-6 also activates NF-κB in the nucleus via cytokine MyD88, CD4, and AP-1, and this activation leads to biological effects that play a role in the process of inflammation and tumor invasion." (PMID 41153795, 2025). "Our results showed a significant increase in levels of expression of inflammatory cytokine IL-1 β (p < 0.01), IL-6 (p < 0.001), TNF-α (p < 0.001), and other related genes including TRAF6 (p < 0.01), MYD88 (p < 0.01), and GDF-15 (p = 0.005) in tumor-bearing mice compared to controls." (PMID 39394174, 2024). "Furthermore, in triple-negative breast cancer, the downregulation of TLR5 has been observed to enhance tumor aggressiveness and promote EMT via the TRAF6 and SOX2 pathways." (PMID 38169510, 2024). "Simultaneously, we found tumor macrophages expressing solely either TLR3, SNCA, or TRAF6 in the tumor-containing lymph, whereas tumor-free lymph macrophages had a significantly higher expression of the combination of these markers, suggesting the presence of the diversified tumor macrophages." (PMID 38719996, 2024). "So, SPHK1 and TRAF6 as tumor promote factors are closely related in CRC, and SPHK1 may regulate the expression of TRAF6." (PMID 38135696, 2024). "Through GSE dataset analysis and in vitro experiments, another controlling network with circ_0001955/ miR-516a-5p/ TRAF6 and MAPK11 axis, it has also been reported that circ_0001955 can facilitate HCC tumor growth by sponging miR-516a-5p to boost TRAF6 and MAPK11 expression." (PMID 36769372, 2023). "Notably, the ablation of E3-ubiquitin ligases of Akt TRAF6, Skp2 and TRAF4 impairs tumor progression in vivo." (PMID 36769122, 2023). "Downregulation of Ube2o in alveolar macrophages (AMs) triggers TAK1- NF-κB/ERK/JNK signaling and CXCL10-induced CCL12 expression by inducing TRAF6 polyubiquitination and blocking DDX3X degradation in tumor environment, resulting in mo-MDSCs recruitment through the CXCL1-CXCR3/TLR4-CCL12 axis." (PMID 36439186, 2022). "Furthermore, knockdown of the MALT1 interaction partner TRAF6 abolishes NF-κB activation, pinpointing the importance of MALT1 as a scaffold protein to bridge TRAF6 to the IKK complex in response to EGF in this tumor entity." (PMID 35203553, 2022). "Similarly, at PCa study, miR-141-3p has been found down regulated, acting as a tumor suppressor that targets TRAF5 and TRAF6." (PMID 33413466, 2021). "As an important tumor repressive gene, TXNIP expression induced by NaBu is TRAF6‐dependent." (PMID 31578830, 2020). "In summary, the present study demonstrates the tumour‐suppressive role of miR‐605‐3p in HCC metastasis for the first time and indicates the importance of the interactions between SNHG16, miR‐605‐3p, TRAF6 and the NF‐κB pathway in the regulation of HCC cell malignancy." (PMID 32436333, 2020). "TRAF6 expression levels were assessed further by IHC in an independent cohort of 42 ES samples, which highlighted an absence of TRAF6 within the ES tumour cells and provided spatial resolution of TRAF6 localisation in tumours." (PMID 31722230, 2020). "Among those molecules, TRAF1, TRAF2, TRAF4, TRAF5 and TRAF6 might play carcinogenic roles, whereas TRAF3 acts as a tumor suppressor." (PMID 32905356, 2020).
tumor (continued). "In light of this and our other findings, the development of therapeutic TRAF6 inhibitors may yield highly effective agents for sabotaging this posttranslational mode of regulating FOXP3 activity and fully unleashing the anti‐tumor immune response." (PMID 30886050, 2019). "Moreover, the downregulation of miR-516a-5p and upregulation of TRAF6 and MAPK11 were confirmed by qRT-PCR in HCC tumor samples (P < 0.05)." (PMID 31822654, 2019). "Additionally, the levels of TRAF6, BRD4, and NFATc1 expression, IκB-α degradation, and p65 nuclear translocation were higher in blood mononuclear cells from tumor samples than in those from normal group at basal levels." (PMID 30455393, 2019). "Our results suggested that downregulation of TLR5 in TNBC increased tumor invasiveness and EMT expression via TRAF6 and SOX2 pathway and TLR5 could serve as a prognostic and monitoring indicator for TLR5-positive tumors." (PMID 31852883, 2019). "TRAF6 upregulates HIF-1a expression and promote tumor angiogenesis in colon cancer." (PMID 29463844, 2018). "Subsequently, we observed a stronger immunoreactivity in SCCHN with lymph node metastasis in comparison with metastasis‐negative SCCHN, and an elevated expression of TRAF6 in metastatic lymph node than in its original tumour." (PMID 29193723, 2018). "The mRNA and protein expressions of TRAF-6, NF-κB and AP-1 in the splenocytes of MyD88−/− tumor-bearing mice were not provoked by APS." (PMID 28303957, 2017). "Besides, the mRNA and protein expressions of TLR4, TRAF-6, NF-κB and AP-1 in the splenocytes of the TLR4+/+ EAC tumor-bearing mice were also observed increased significantly." (PMID 28303957, 2017). "Furthermore, the APS-induced TLR4, TRAF-6, NF-κB and AP-1 expression were decreased in the splenocytes of the TLR4−/− EAC tumor-bearing mice." (PMID 28303957, 2017). "It was also reported that TRAF6 increases HIF-1α expression and promotes tumor angiogenesis." (PMID 26769849, 2016). "Both PDCD4 and TRAF6 were expressed in the astroglial component of the tumor, and a negative correlation was observed between the PDCD4 IRS and the miR21 (r = −0.817, p = <0.001), as well as between the TRAF6 IRS and the miR146a (r = −0.498, p = < 0.05)." (PMID 25986346, 2015). "Accordingly, we observed a negative correlation between the level of tumor miR146a and the expression of TRAF6, a downstream signaling molecule of the TIR signaling pathway that has previously been shown to be a miR146 target." (PMID 25986346, 2015). "MiR-146a has a growing list of presumed targets including, TRAF6, IRAK1, CXCR4, NF-κB, which may contribute to inflammation and tumor development." (PMID 25490205, 2014). "Additionally, we verified that TRAF6 could facilitate PKM2‐mediated glycolysis and chemoresistance in animal models and clinical tumor tissues." (PMID 37746908, 2023). "Considering that overexpression of DRAK1 suppresses TRAF6-mediated NF-κB signaling, thereby attenuating cell growth and tumorigenesis of HeLa/PTX cells, we investigated whether DRAK1 alters the expression of genes involved in tumor progression." (PMID 35194034, 2022). "In addition, the inhibition of some of these markers, using Ang1 analogs, inhibitors of EGFR, TRAF6, or combined inhibitors of EGFR and IGF-IR, may lead to a decrease in tumor size." (PMID 35956111, 2022). "Therefore, the use of PPI inhibitors to inhibit the combination of TRAF6 and ECSIT may play a role in tumor suppression." (PMID 32905356, 2020). "MC-38 tumor cells with reduced TRAF6 expression could not establish a tumor in the caecum, while tumors readily formed upon subcutaneous injection, albeit at a reduced size." (PMID 33142239, 2020). "Intestinal epithelial cells are in a constant contact with microbiota, which requires a tight control of inflammatory responses, likely explaining why tumor cells with reduced TRAF6 activity and therefore reduced NF-κB signaling do not grow in the inflammatory environment of a colon." (PMID 33142239, 2020).
tumor (continued). "Thus tRXRα activation of the NF-κB pathway in macrophages through its interaction with cytoplasmic TRAF6 represents an important non-transcriptional mechanism by which tRXRα promotes tumor growth." (PMID 30931933, 2019). "In tumor bearing mice, the ER stress markers such as p-eIF2α, CHOP, IRE1α, XBP1, ATF6, DR5, GRP78, GRP94, GADD34, and sXBP1 were found to be substantially elevated as well as correlated with increased ubiquitylated protein levels and heightened expression of E3 ligases: MAFBx, MuRF1, TRAF6." (PMID 31817027, 2019). "Meanwhile, confronted with “metabolic competition”, lack of glucose impairs T cell’s anti-tumor immunity and secretion of Interferon-γ (IFN-γ), while low lipid support results in TNF receptor associated factor 6 (TRAF6) deficiency, which inhibits long-lasting memory CD8+ T cells formation." (PMID 29458370, 2018). "In addition, TRAF6 is reported to increase HIF-1α expression and promote tumor angiogenesis." (PMID 27791197, 2016). "Twenty five days after administration, TLR4, TRAF6, NF-κB and AP-1 in PSP and LPS group (positive control) were significantly increased at mRNA and protein level relative to those of the saline group in the spleen of B10 (TLR4+/+) tumor-bearing mice (all p < 0.05)." (PMID 26032186, 2015). "Although it seems likely that other factors in addition to miR-146a may be involved in the down-regulation of IRAK1 and TRAF6 during the progression of OSCC, the effects of miR-146a expression in modulating IRAK1 down-regulation can be shown in advanced tumor samples." (PMID 24302991, 2013). "For miR-146a, NF-κB dampening through IRAK1/TRAF6 targeting can reduce inflammatory cytokines and support anti-tumor immunity, yet in specific inflammatory milieus negative-feedback regulation may also favor tumor persistence by blunting acute immune activation." (PMID 41226828, 2025). "Furthermore, tumour tissues showed significantly decreased expression of cytoplasmic microbial sensors (NOD1 and NOD2) and downstream signaling molecules for innate microbial sensors such as CARD6, CARD9, and TRAF6 (p = 0.0207, p = 0.0040, and p = 0.0119, respectively)." (PMID 37007104, 2023). "Furthermore, TRAF6‐conferred poor prognosis is independent of tumour size or pathological grades." (PMID 29193723, 2018). "Moreover, TRAF-6 and NF-κB were not triggered by APS in gene-deficient tumor-bearing mice." (PMID 28303957, 2017). "In summary, APS induces the expressions of mRNAs and proteins of TLR4, TRAF-6, NF-κB and AP-1, as well as increasing the levels of TNF-α and IL-6 in the serum of the TLR4+/+ tumor-bearing mice, but not TLR4−/− tumor-bearing mice." (PMID 28303957, 2017). "Interestingly, while TWEAK secretion is not high in PDAC tumor cells, macrophages can respond to tumor cell-secreted CCL2, activate and secrete CCL5, and significantly upregulate TWEAK expression and secretion in tumor cells via the TRAF6/NF-κB pathway." (PMID 38982491, 2024). "Interestingly, TRAF6 interacted with tRXRα but not with RXRα, demonstrating that tRXRα activation of the IKK-NF-κB pathway is a tumor-specific event." (PMID 30931933, 2019). "However, elevated TRAF6 expression was not significantly correlated with pathological grades (I–III) and tumour size (T1–T4)." (PMID 29193723, 2018).
cancer (161 papers, 2009 to 2026). A tumor composed of atypical neoplastic, often pleomorphic cells that invade other tissues. "Numerous studies have confirmed that TRAF6 is closely associated with tumorigenesis and is a potential target in malignant tumors." (PMID 40296903, 2025). "TRAF6 is frequently overexpressed in malignant tumors and is associated with poor patient prognosis." (PMID 41419456, 2025). "Analysis of the GEPIA and KM plotter databases showed its high expression correlated with poor patient prognosis, consistent with the previous reports that TRAF6 overexpression is associated with progression of many cancers." (PMID 39706834, 2024). "TRAF6 has the potential to be an effective target in treating cancers; however, the underlying mechanisms of resistance to TRAF6 and radiotherapy have been partially elucidated." (PMID 38169510, 2024). "Here, through screening the E3 ligase library we found that TRAF6 interacts with and positively regulates PD-L1 stability through promoting the K63-linked ubiquitination of PD-L1 in cancer cells." (PMID 35361799, 2022). "In contrast, TLR4 enhances autophagy induction through beclin 1 (BECN1) ubiquitination by TNF receptor-associated factor 6 (TRAF6) promoting cell migration and invasion in various cancer cell lines." (PMID 34575052, 2021). "TRAF6 mRNA was found to be over expressed in cancer, but the mechanisms underlying this increased expression have not been determined yet." (PMID 32344511, 2020). "As expected, the examined cancer-specific characteristics of the cells caused by miR-146-5p overexpression were all reversed by TRAF6 plasmid co-transfection." (PMID 33015045, 2020). "In our current study, risk groups defined by expression of TRAF6 and level of differentiation were the only predictors of cancer specific survival of OSCC patients." (PMID 29703234, 2018). "Functional significance of these TRAF6 recurrent mutations in cancer pathogenesis remains to be elucidated." (PMID 30294322, 2018). "There are 178 different mutations of TRAF6 detected in human cancers, comprising 85% (152/178) mutations that alter the protein sequence of TRAF6 and 15% (26/178) coding silent mutations." (PMID 30294322, 2018). "Only 27% (41/152) of the coding-altering mutations of TRAF6 are recurrently detected in at least two cancer patients." (PMID 30294322, 2018). "The ubiquitin-ligase tumour necrosis factor receptor-associated factor 6 (TRAF6) was recently linked to regulate intramembrane proteolytic cleavage of the TβRI in cancer cells." (PMID 26583432, 2016). "TRAF6 deficiency inhibits the induction of atrophy program in response to starvation, denervation, or cancer cachexia by suppressing the expression of key regulators of atrophy, including MAFBx, MuRF1, p62, LC3B, Beclin1, Atg12, and Fn14." (PMID 23758787, 2013). "Tumor necrosis factor receptor‐associated factor 6 (TRAF6), as an E3 ubiquitin ligase, has a significant function in cancer biology processes by triggering cell signaling pathways, including, the NF‐κB signaling pathway, the MAPK signaling pathway, and the Wnt/β‐catenin signaling pathway." (PMID 37746908, 2023). "Loss of TRAF6 impairs K63-linked ubiquitination, membrane recruitment and activation of Akt, resulting in reduced prostate tumor growth, making it a promising novel anti-cancer target." (PMID 36180910, 2022). "IL-33/ST2 signaling activates myeloid differentiation primary response 88 (MyD88)/interleukin-1 receptor (IL-1R) associated kinase (IRAK)/TNF receptor-associated factor 6 (TRAF6) pathway in the majority of cell types, including cancer cells, stromal cells, and immune cells." (PMID 34209038, 2021). "High expression of TRAF6 is associated with poor prognosis in cancer patients." (PMID 33294443, 2020).
cancer (continued). "Studies have found that E3 ligase TRAF6, which is upregulated in cancer cells, can mediate K63-linked polyubiquitination of mTOR by interacting with p62 under the stimulation of amino acids, promoting the translocation of mTORC1 to the lysosomes and subsequent activation." (PMID 33004065, 2020). "Moreover, p62 binds TNFR-associated factor 6 (TRAF6) with the TRAF6-binding domain (TB) to activate NF-κB signalling, resulting in the expression of inflammatory genes and cancer metastasis." (PMID 31708690, 2019). "However, in cancer cells, TRAF6-mediated K63-linked polyubiquitination of TβRI also promotes cleavage of TβRI by TNFα converting enzyme (TACE) in a PKCζ-dependent manner." (PMID 23758787, 2013). "We hope this review can provide a comprehensive perspective on TRAF6-targeted therapeutic strategies for cancer." (PMID 42121919, 2026). "This review summarizes the structural features, substrate diversity, and multifaceted roles of TRAF6 in cancer, as well as the development of TRAF6-targeting drugs and strategies." (PMID 42121919, 2026). "It has been suggested that TRAF6 functions as a key factor in skeletal muscle atrophy, including cancer cachexia." (PMID 40869331, 2025). "We found that the Akt–GSK3β axis can be regulated by TRAF6, which is consistent with the literature on the role of Pim1 in cancer." (PMID 40164682, 2025). "There are seven members of the tumor necrosis factor receptor-related factors (TRAFs) family, among which TRAF6 is up-regulated in various malignant tumors and closely related to tumorigenesis and progression." (PMID 40296903, 2025). "Protein chip analyses of CRC tissue samples, CCL3 was found to be highly expressed and closely related to the TLR/TRAF6/NF‐κB pathway, which facilitates invasion and proliferation of cancer cells." (PMID 40727252, 2025). "Multiple studies support that miR-146a influences the expression of genes involved in cancer progression and metastasis by modulating key signaling pathways, including TNFα/TRAF6, IFNγ/STAT, GPCR, PI3K-AKT-mTOR, and TGFβ/SMAD." (PMID 40277937, 2025). "Data from both mouse models of cancer cachexia and muscle specimens from human cancer patients have shown that TRAF6 expression and activity are enhanced in atrophying skeletal muscle." (PMID 40869331, 2025). "As an E3 ubiquitin ligase, the mediation of AKT ubiquitination and subsequent phosphorylation by TRAF6 has emerged as a critical determinant in cancer progression." (PMID 38169510, 2024). "Another exosomal miRNA, miR-146a-5p, has been linked to NSCLC cell survival and migration by directly inhibiting the inhibitory functions of TRAF6 on cancer cell proliferation, migration, and resistance to apoptosis." (PMID 39409003, 2024). "Functionally, CCL3 promotes cancer growth by stimulating proliferation, migration, and invasion, acting via the TRAF6/NF-κB pathway." (PMID 38338661, 2024). "Considering the dynamic interplay between cancer cells and their microenvironments, TRAF6 in immune cells play a critical role in cancer progression." (PMID 38169510, 2024). "Subsequent chapters will elucidate the involvement of TRAF6 in cancer, aiming to provide valuable perspectives on novel avenues for cancer therapeutic strategies." (PMID 38169510, 2024). "An increase in TRAF6 expression has been reported in the majority of human malignant neoplasms 36-39." (PMID 38169510, 2024). "Taken together, these contrasting discoveries highlight the intricacies embedded in cancer management and underscore the imperative to elucidate the specific functional roles of disparate molecular mechanisms related to TRAF6 in the context of CRC." (PMID 38169510, 2024). "This association can be attributed to the widespread overexpression of TRAF6 across various types of human cancer, arising from the abnormal proliferation, differentiation, and apoptosis of neoplastic cells." (PMID 38169510, 2024).